NOX4 (NADPH oxidase 4)
Diseases named in the same sentence as NOX4 in open-access papers (continued):
Sharing a sentence is not in itself a finding about the gene and the disease.
Cognitive impairment (6 papers, 2017 to 2026). Abnormal cognition is characterized by deficits in thinking, reasoning, or remembering. "Critically, NOX4-knockout mice resisted P.g-induced cognitive impairment, neuronal loss, and neuroinflammatory responses in vivo." (PMID 41960571, 2026). "We also demonstrated, for the first time, that this cognitive impairment was mediated by the expression and aggregation of Aβ in the hippocampus and was associated with an increase in NOX4 expression in the hippocampal DG." (PMID 30736297, 2019). "To investigate the mechanism of inhibition of cognitive impairment caused by NOX4 knockdown, we examined the effects of NOX4 upregulation in the hippocampal DG of MFB-injured mice on the expression of α-syn and Aβ on protein aggregation in hippocampal tissues." (PMID 30736297, 2019). "There was a high correlation between cognitive impairment and A11 oligomer production, NOX4, and Aβ expression, except for NOX1 expression." (PMID 30736297, 2019). "We showed that the upregulation of NOX4 in the DG of the hippocampus was accompanied by cognitive impairment and led to increases in Aβ expression and oligomer A11 production." (PMID 30736297, 2019). "Changes in NOX4 expression were highly correlated with cognitive impairment." (PMID 30736297, 2019). "In addition, hippocampal Aβ expression, A11 oligomer formation, and cognitive impairment were attenuated by genetic interventions targeting NOX4 in the hippocampal DG." (PMID 30736297, 2019). "Several studies have shown that cognitive impairment in age- or AD-related transgenic mice occurs through an increase in NOX activity and an increase in the expression of NOX2 and NOX4, which lead to oxidative stress and amyloid deposition." (PMID 30736297, 2019). "6-OHDA dose-dependent cognitive impairment was observed, and the increased cognitive impairment, Aβ expression, and oligomer A11 production in 6-OHDA-treated mice were suppressed by NOX4 knockdown in the hippocampal DG." (PMID 30736297, 2019).
COVID-19 (6 papers, 2021 to 2025). A disease caused by infection with severe acute respiratory syndrome coronavirus 2. "The ratio between NOX4 and Nrf2 expression was increased in both COVID-19 variants, which indicates that the protective effects of Nrf2 are outweighed by the oxidative effects of NOX4." (PMID 36498845, 2022). "Nrf2 was unaffected in COVID-19/B.1 variant but increased in COVID-19/B.1.1.7 variant (p < 0.0001 vs. COVID-19/B.1 patients), whilst NOX4 was upregulated in both COVID-19 variants." (PMID 36498845, 2022). "As observed in gene expression results, the expression of TLR2/MyD88 and NOX4/Nrf2 was also overexpressed in COVID-19 patients." (PMID 36498845, 2022). "Accordingly, we demonstrate here increased levels of both NOX2 and NOX4 mRNA in left ventricular tissue from patients with COVID-19." (PMID 34745111, 2021). "Taken together, the increased expression of ACE2, NOX4, NF-κB, and ASC indicate that severe cases of COVID-19 suffered from an increased inflammasome complex activation even when compared to H1N1 and to a control group with chronic inflammatory illnesses." (PMID 36361818, 2022).
fibrosarcoma (6 papers, 2017 to 2022). A malignant mesenchymal fibroblastic neoplasm affecting the soft tissue and bone. "According to those findings, in vivo, in a murine inflammation-driven fibrosarcoma model, Nox4 deficiency forces the expression of proinflammatory genes and cytokines, accompanied by an increase in the number of proinflammatory Ly6C+ macrophages in the tumors." (PMID 31178956, 2019). "In a carcinogen 3-methylcholanthrene (MCA)-induced fibrosarcoma mice model, there is a significant 38% reduction in tumor vascularization in fibrosarcomas of NOX4−/− mice." (PMID 28594389, 2017). "In a carcinogen 3-methylcholanthrene (MCA)-induced fibrosarcoma mice model, NOX4 was proved to regulate the tumour-vessel density through stabilization of HIF-1α and induction of VEGF expression, while a significant 38% reduction in tumour vascularization in fibrosarcomas of Nox4-/- mice." (PMID 34930338, 2021). "In Nox4 knockout mice with fibrosarcoma, vessel density analysis showed a significant reduction in tumor vascularization, leading to the attenuation of hypoxia-inducible factor 1-alpha, vascular endothelial growth factor, glucose transporter 1 and adrenomedullin." (PMID 30513726, 2018). "In a murine fibrosarcoma model, the absence of Nox4 forces tumor growth." (PMID 31178956, 2019). "Furthermore, observations with Nox4 knock-out mice indicate the absence of Nox4 results in several proinflammatory phenotypes, including increased macrophage Nox2 expression and enhanced infiltration of proinflammatory macrophages in tumors of an induced fibrosarcoma model." (PMID 33557266, 2021).
glomerulosclerosis (6 papers, 2014 to 2025). A hardening of the kidney glomerulus caused by scarring of the blood vessels. "The glomerular sclerosis, mesangiolysis, and the tubulointerstitial sclerosis index were not changed by the treatment, with the exception that mesangiolysis increased in the angiotensin II-treated Nox4 knockout animals." (PMID 32635630, 2020).
head and neck squamous cell carcinoma (6 papers, 2015 to 2025). A squamous cell carcinoma that arises from any of the following anatomic sites: lip and oral cavity, nasal cavity, paranasal sinuses, pharynx, larynx, and salivary glands. "The ANGPTL4/NOX4 axis is critical for tumor cell extravasation and metastatic seeding of tumor cells in dyslipidemia-associated cancer like kidney cancer, head and neck squamous cell carcinoma and so on." (PMID 36829161, 2023). "A recent study reported that specific EGFR tyrosine kinase inhibitor erlotinib induce IL-6 expression in head and neck squamous cell carcinoma through NOX4/p38 and JNK/ NF-κB pathway." (PMID 26513016, 2015). "All the head and neck squamous cell carcinomas, regardless of their origin, expressed NOX4; most (approximately 80%) were high positive." (PMID 28578276, 2017).
lymph node metastasis (6 papers, 2018 to 2024). "In the meta-analysis, higher NOX4 expression was linked to both a shorter overall survival rate (HR = 1.93, 95% CI 1.49–2.49, P < 0.001) and a higher percentage of lymph node metastases (OR = 3.22, 95% CI 2.18–4.29, P < 0.001)." (PMID 38012557, 2023). "The results suggest that NOX4 appears to have an important effect on survival in patients with low lymph node metastases and in patients with carcinoembryonic antigen (CEA) negative." (PMID 36874093, 2023). "Lymph node metastasis was demonstrated to be more likely when NOX4 expression was greater (OR = 2.93, 95% CI 2.18–4.31, P < 0.001)." (PMID 38012557, 2023). "This study found that increased NOX4 expression was associated with worse OS and DFS and an increased incidence of lymph node metastases." (PMID 38012557, 2023). "The expression of NOX4 in GC was significantly relevant to tumor size, lymph node metastasis, venous invasion, and unfortunate survival." (PMID 36685842, 2022). "The current study found that Nox4 and lymph node metastasis were both prognostic factors for patients with OTSCC in the univariate and multivariable analyses." (PMID 30513726, 2018). "The univariate analysis suggested that tumor histological type, differentiation degree, Nevin stage, liver metastasis, vascular invasion, lymph node metastasis, resection method, NOX4 expression in tumor cells/GCAFs were significant prognostic indicators for the OS of GBC patients (all P < 0.05)." (PMID 33153467, 2020). "We found the highest expression of NOX4 in pancreatic body tumors, and in patients with Tumor Size less than 7 cm, with moderate lymph node metastasis, no vascular recidivism or no distant metastasis, high expression of NOX4 was detected in the pancreas." (PMID 36874093, 2023).
sarcopenia (6 papers, 2013 to 2026). Progressive decline in muscle mass due to aging which results in decreased functional capacity of muscles. "For sarcopenia, the risk score was: normalized expression of NOX4 × 2.229 + normalized expression of NEK6 × (–2.369)." (PMID 40977679, 2025). "Elevated NOX4 expression may contribute to muscle atrophy via ROS-mediated mitochondrial dysfunction and protein degradation, both of which are implicated in the pathogenesis of sarcopenia." (PMID 40977679, 2025). "NOX4 (AUC = 0.798, 95% CI: 0.633 – 0.962) and NEK6 (AUC = 0.873, 95% CI: 0.749 – 0.996) exhibited high diagnostic accuracy for SSc-associated sarcopenia." (PMID 40977679, 2025). "This study identified NOX4 and NEK6 as dual diagnostic biomarkers for SSc-associated sarcopenia through integrative bioinformatics and machine learning approaches." (PMID 40977679, 2025). "To assess the diagnostic utility of NOX4 and NEK for sarcopenia in SSc, we performed a Pearson correlation analysis with ASMI." (PMID 40977679, 2025). "In the sarcopenia dataset, the AUC for NOX4 was 0.662 (95% CI: 0.524 – 0.801), and for NEK6, it was 0.661 (95% CI: 0.533 – 0.789), suggesting limited individual predictive efficacy in sarcopenia." (PMID 40977679, 2025). "Our results establish NOX4 and NEK6 as novel diagnostic biomarkers for SSc-associated sarcopenia and propose a non-invasive strategy for its early detection." (PMID 40977679, 2025). "NOX4 is also an important source of ROS, which promotes the sarcopenia onset, suggesting that NADPH oxidase is a potential therapeutic target to counteract age-related muscle atrophy." (PMID 39846667, 2025). "This study proposes NOX4 and NEK6 as novel biomarkers, offering a non-invasive strategy for the early detection of SSc-associated sarcopenia." (PMID 40977679, 2025). "PCR validation confirmed the differential expression of NOX4 and NEK6 in both SSc and SSc-associated sarcopenia, demonstrating high predictive accuracy." (PMID 40977679, 2025). "A study with female Balb/c mice of different ages showed that NOX2 and NOX4 were higher in the quadriceps of older animals, related to the onset of sarcopenia." (PMID 27847553, 2016). "The results from this study indicate the potential for NOX4 as a subcellular regulator of O2 ̅ and suggests further investigation into its localization and thereby its role in skeletal muscle and sarcopenia." (PMID 24093947, 2013). "The model positions NOX4 and NEK6 as pivotal contributors to SSc-associated sarcopenia." (PMID 40977679, 2025). "This pattern may indicate that NOX4 and NEK6 may have an potential association between SSc and sarcopenia." (PMID 40977679, 2025). "In order to more precisely evaluate the variations in their expression levels and determine whether there is statistical significance, we therefore intend to increase the sample size in subsequent research on NOX4 and NEK6 in SSc associated sarcopenia." (PMID 40977679, 2025). "Five key CGs—NOX4, STC2, NEK6, IGSF10, and EMX2—were identified as molecular links between SSc and sarcopenia." (PMID 40977679, 2025). "In the sarcopenia dataset GSE167186, NOX4 expression was elevated, and NEK6 expression was reduced in sarcopenia patients compared with controls." (PMID 40977679, 2025). "In agreement, Wu and colleagues administered Benzo[a]pyrene to the murine C2C12 cell line to reproduce an oxidative stress condition triggering sarcopenia development, finding an increased ROS production mediated by NOX2 and NOX4." (PMID 40692696, 2025). "In the sarcopenia dataset (GSE167186), the individual AUC values for NOX4 and NEK6 were 0.662 (95% CI: 0.524 – 0.801) and 0.661 (95% CI: 0.533 – 0.789) respectively." (PMID 40977679, 2025). "The results revealed that NOX4 expression was elevated in both the SSc sarcopenia and non-sarcopenia groups compared to healthy controls." (PMID 40977679, 2025).
systemic sclerosis (6 papers, 2018 to 2024). A chronic disorder, possibly autoimmune, marked by excessive production of collagen which results in hardening and thickening of body tissues. "Increased NOX4 expression has been observed in the skin of patients with systemic sclerosis and in experimental models of skin fibrosis." (PMID 39223490, 2024). "Analyses of human dermal fibroblasts (HDFs) from patients with systemic sclerosis confirmed the expression of Nox4, whereas Nox1 and Nox2 were not detectable, indicating that Nox4 targeting is a promising future treatment for fibrotic skin diseases." (PMID 29538284, 2018). "A gene array analysis showed increased NOX4 gene expression and decreased SOD2 expression in systemic sclerosis (SSc) and IPF lung fibroblasts compared to non-fibrotic controls." (PMID 37686037, 2023).
tendinopathy (6 papers, 2020 to 2025). "One of the examples is the increased expression of NOX1 and NOX4 in rat cultured tenocytes and Achilles’ tendons with collagenase-induced tendinopathy concomitant with elevated ROS levels following the stimulation with nicotinamide mononucleotide." (PMID 40023978, 2025). "NOX4 has also been shown to play a role in the chondro-osteogenic phenotype observed in tendon cells during tendinopathy." (PMID 38247510, 2024). "HIF-1 has been documented to promote the expression of the NOX family, particularly NOX1 and NOX4, which are highly elevated in oxidative-stress-induced tendinopathy animal models." (PMID 38247510, 2024). "After 2 weeks of treatment, immunostaining revealed significantly suppressed NOX1 and NOX4 levels in the Achilles tendons of the NMN group compared to the control in a collagenase-induced tendinopathy model (p = 0.043 and p = 0.021, respectively)." (PMID 35287653, 2022). "Our study indicated Nox4 and IRS1 as the therapeutic targets of tendinopathy; however, further research is needed to clarify the functional mechanism of Nox4 and IRS1 in chondro-osteogenesis in tendinopathy." (PMID 31065679, 2020). "This indicates that NOX4-derived ROS under hypoxia play a role in the pathogenesis of tendinopathy." (PMID 38247510, 2024). "Note that Nox4 in tendon disease was first analyzed in our study." (PMID 31065679, 2020). "Furthermore, we tested the in situ expression of IRS1 and Nox4 in human tendinopathy samples." (PMID 31065679, 2020). "Both in rat cultured tenocytes and in Achilles’ tendons with collagenase-induced tendinopathy levels of IL6, ROS and NOX1 and NOX4 were increased while SIRT1 and SIRT6 were decreased together with SOD activity." (PMID 40023978, 2025). "In Achilles tendons with collagenase-induced tendinopathy, NMN increased the mRNA expression of SIRT1 and SIRT6, as well as SOD activity; while suppressing protein expression of NOX1 and NOX4, and mRNA expression of IL6." (PMID 35287653, 2022). "Taken together, we deduced that miR-337-3p can be a therapeutic target of tendinopathy through downregulating chondro-osteogenic differentiation of rTDSCs by targeting IRS1 and Nox4 as elucidated in the schematic diagram." (PMID 31065679, 2020). "In vitro and in vivo studies by Yamaura and colleagues showed that NMN has antioxidant effects against tendinopathy and promotes the expression of SIRT 1 and SIRT 6, known for their anti-aging and anti-inflammatory roles, while reducing the expression of NOX1, NOX4, Il-6, and ROS." (PMID 38247510, 2024). "During tendinopathy, hypoxia promotes the expression of HIF-1α, NOX1, and NOX4." (PMID 38247510, 2024). "Most importantly, the expression of IRS1 and Nox4 was as predicted increased, especially in the abnormal cell proliferation zone, which validated that IRS1 and Nox4 are positively related to tendinopathy." (PMID 31065679, 2020). "Also the expression of miR-337-3p was also downregulated in the calcification tendon of tendinopathy patients, with increased IRS1 and Nox4 tested by real-time PCR." (PMID 31065679, 2020).
urothelial carcinoma (6 papers, 2011 to 2025). A malignant neoplasm derived from the transitional epithelium of the urinary tract (urinary bladder, ureter, urethra, or renal pelvis). "NOX4 is expressed at very low levels in human normal urothelium whereas NOX1, NOX2, and NOX4 are overexpressed in urothelial carcinoma patients." (PMID 36670953, 2022). "In urothelial carcinoma, NOX4, which is detected already in precancerous and in early noninvasive urothelial carcinoma, has been shown to stimulate cell cycle progression and cancer cell growth." (PMID 29478325, 2019). "This is the first study showing that the NOX4-ROS signal contributes to the survival of human urothelial carcinoma cells via progression of the G1/S transition." (PMID 22032647, 2011). "NOX4 contributes to ROS production and cell survival in human urothelial carcinoma cells." (PMID 22032647, 2011). "Therefore, in addition to NOX1, NOX4 is required for the maintenance of intracellular ROS in urothelial carcinoma cells." (PMID 22032647, 2011). "Since the NOX4-ROS signal was strongly amplified in urothelial carcinoma cells, unlike in normal urothelial cells, we attempted to clarify the usefulness of ROS labeling in cytological diagnosis." (PMID 22032647, 2011). "Since NOX4 has been found in urothelial carcinoma and precancerous lesions but not in normal urothelium, NOX4 might be a pivotal enzyme to ROS generation, contributing to the early steps of urothelial carcinogenesis." (PMID 34073079, 2021).
cardiac arrhythmia (5 papers, 2020 to 2025). Any disturbances of the normal rhythmic beating of the heart or MYOCARDIAL CONTRACTION. "Altogether, evidence from zebrafish and human studies suggest that NOX4 upregulation promotes oxidative stress, calcium handling abnormalities, and structural remodeling, thereby facilitating the development of cardiac arrhythmias, particularly AF." (PMID 41009041, 2025). "Inhibition of NOX4 could therefore mitigate the pathogenesis of AF, suggesting that NOX4 targeting could offer a potential strategy for controlling the progression of this arrhythmia." (PMID 41009041, 2025).
endotoxemia (5 papers, 2021 to 2025). "Cinnamaldehyde inhibits intracellular ROS production and suppresses TLR4 and NOX4 during LPS-induced endotoxemia." (PMID 40572518, 2025). "In addition, ANC alleviated endotoxemia as well as decreased NOX4 and TNFα overexpression along with JNK phosphorylation, indicating that it could alleviate the inflammatory and pro-oxidant conditions stimulated by extra fat uptake." (PMID 41585869, 2025).
Hypercholesterolemia (5 papers, 2013 to 2024). An increased concentration of cholesterol in the blood. "Previous studies suggested a role of NOX4 in cell growth, apoptosis, senescence, and autophagy of aortic smooth muscle cells during hypercholesterolemia." (PMID 37873768, 2023). "In a recent study, hypercholesterolemia increased NOX4 expression and the consequent oxidative stress in the heart by down-regulating microRNA-25 (Entrez Gene: 407014)." (PMID 24392026, 2013). "However, recently, miR-25 has been found to repress NOX4 expression in hypercholesterolemia-induced myocardial dysfunction rats." (PMID 24528626, 2014). "Hypercholesterolemia is also known to induce TGF-β signaling, which in turn induces NOX4." (PMID 38790608, 2024).